CD4 (CD4 molecule)
Diseases named in the same sentence as CD4 in open-access papers (continued):
Sharing a sentence is not in itself a finding about the gene and the disease.
lung adenocarcinoma (continued). "In this study, we also revealed down-regulation of IL-22 secretion and AhR mRNA expression, but comparable RORγt mRNA level, in lung-resident CD4+ T cells in response to Notch signaling inhibition in lung adenocarcinoma patients." (PMID 30473538, 2018). "The current data indicated that elevated Notch1 induced higher IL-22 secretion by CD4+ T cells in lung adenocarcinoma patients, and Notch-AhR-IL-22 axis took part in the pathogenesis of lung adenocarcinoma." (PMID 30473538, 2018). "In one study, the role of ethanol and CD4+ T cells in controlling tumor growth was examined by implanting 201T human lung adenocarcinoma cell line into the lung of ethanol-fed BALB/c mice that also received anti-CD4 antibody." (PMID 28805741, 2017). "A549 lung adenocarcinoma cells carrying a GFP- or CD4 reporter were transduced with individual shRNAs at high multiplicity of infection and then pooled." (PMID 28447610, 2017). "In summary, our results show that, at the systemic level, the percentage of the LAP TGF-β1+ subset of CD4+CD25+CD127− Treg cells was increased in advanced-stage lung adenocarcinoma patients." (PMID 26582240, 2015). "Approximately 50–60% of the CD4+CD25+CD127− Treg cells expressed CTLA-4 in lung adenocarcinoma patients and the control groups." (PMID 26582240, 2015). "In peripheral blood of lung adenocarcinoma patients, higher proportions of CD4+ROR-γt+ T-cells compared with the IL-17-producing Th17 cells were found." (PMID 26582240, 2015). "Further studies revealed that upregulation of FOXF1/MFAP4 promoted anti-tumor immune responses through augmented dendritic cell and CD4+ T cell infiltration, facilitating crosstalk between lung adenocarcinoma and immune cells, and induction of multiple anti-tumor immune pathways." (PMID 41596347, 2026). "Additionally, patients with lung adenocarcinoma with low expression of miR-30a-5p exhibit increased infiltration of B cells, CD4+, T cells, and macrophages, and this infiltration of immune cells is associated with improved patient prognosis." (PMID 40867269, 2025). "Furthermore, an elevated presence of tumor-infiltrating CD4+ FOXP3+ Tregs has been described in patients with the 'mesenchymal' lung adenocarcinoma phenotype in comparison to those with an 'epithelial' lung adenocarcinoma phenotype." (PMID 41023740, 2025). "In our research, based on the ‘ESTIMATE’ and deconvolution algorithms, AUNIP shows a significant positive correlation with tumor purity scores, and a negative correlation with immune scores, B cells, CD8+ T cells, and CD4+ T cells in the lung adenocarcinoma cohort from the TCGA database." (PMID 39148731, 2024). "Interestingly, in a mouse model of lung adenocarcinoma, Treg cells reduced the number and cellular density of TLSs, especially affecting numbers of CD4 and CD8 T cells." (PMID 36077836, 2022). "FOXP3+/CD4+ cell ratio can be used to predict the prognosis of lung adenocarcinoma." (PMID 36385958, 2022). "In addition, lung adenocarcinoma with SDPR arm-level deletion showed less infiltration of CD4+ T cells, macrophages and neutrophils in TME." (PMID 33435990, 2021). "However, ALDOA expression was negatively correlated with infiltrating levels of B cells, CD8+ T cells, CD4+ T cells, and macrophages in lung adenocarcinoma." (PMID 34925439, 2021). "This might explain the reason that correlation between FGL2 and CD4+ T cells was poor and moderate in lung adenocarcinoma." (PMID 32206449, 2020). "Infiltration of activated CD4, CD8, effector memory CD4 T-cells, and Th17 cells were higher in the desmosome overexpression group, whereas infiltration of mast cells, macrophages, Tregs, and activated B-cells were lower in lung adenocarcinoma." (PMID 29348685, 2018). "In lung adenocarcinoma patients, the percentage of CD4+ROR-γt+ T-cells was 2.75%." (PMID 26582240, 2015).
lung adenocarcinoma (continued). "In addition, lung adenocarcinoma patients increased both plasma concentrations of IL-2, IL-4, IL-6, and IL-10, and proportions of Latency Associated Peptide (LAP) TGF-β subset of CD4+CD25+CD127− Treg cells, which overexpressed LAP TGF-β." (PMID 26582240, 2015). "However, a significant increase of 1.4-fold to 1.75-fold was detected in the percentages of CD4+CD25+CD127−LAP TGF-β1+ Treg cells in lung adenocarcinoma patients compared with the corresponding population in the smoking and nonsmoking control groups." (PMID 26582240, 2015). "This knowledge may lead to the development of immunotherapies that could inhibit the suppressor activity mediated by the LAP TGF-β subset of CD4+CD25+CD127− Treg cells to promote reactivity of immune cells against lung adenocarcinoma cells." (PMID 26582240, 2015). "Further GSEA analysis indicated that genes associated with CD4+ Tem cells were significantly downregulated, whereas elevated IGF2BP3 expression correlated with increased Th2-related gene activity, suggesting its potential role in lung adenocarcinoma by influencing immune cell infiltration." (PMID 40801655, 2025). "Moreover, high expression of FLT3LG was significantly positively correlated with increased infiltration of multiple immune cells, including T cells and natural killer (NK) cells, in lung adenocarcinomas, as well as the expression of several immune cell markers, such as CD4 and CD8a." (PMID 40329265, 2025). "Additionally, a positive relationship was identified between TRMT112 expression and multiple tumor-related immune infiltrations, such as dendritic cells, CD8+ T cells, macrophages, CD4+ T cells, neutrophils, and B cells in lung adenocarcinoma and breast invasive carcinoma." (PMID 36081672, 2022). "The authors also observed that CXCL12 correlated with a higher degree of tumor inflammation and suggested that the concomitant presence of activated TILs CD4+CXCR4+ CD69+ might influence tumor progression by shaping the immune cell population infiltrating lung adenocarcinomas." (PMID 35740564, 2022). "Macrophages, monocytes, CD4 T cells, plasma cells, mast cells, and neutrophils were highly expressed in tumor and adjacent nontumorous tissues, suggesting that they may play essential roles in lung adenocarcinoma." (PMID 34395526, 2021). "Furthermore, Tregs inversely correlated with active CD4+ Tmem in lung adenocarcinoma." (PMID 30374348, 2018). "Thus, suggesting that effector responses involving CD4+ T cells and plasma cells could favorably shape clinical outcome in patients with lung adenocarcinoma." (PMID 30374348, 2018). "Furthermore, the estimates of Tregs, macrophages, non-Treg CD4+ T cells, and plasma cell, when considered together, can identify early stage lung adenocarcinoma patients at significantly greater risk of recurrence." (PMID 30374348, 2018). "Therefore, in both lung adenocarcinoma and SCC, overexpression of EAM genes at all steps of adhesion was strongly linked to decreased infiltration of activated CD8 and CD4 lymphocytes, and increased infiltration of Tregs, macrophages, activated B-cells, and NK cells." (PMID 29348685, 2018). "In lung adenocarcinoma patients with a high plasma cell gene score, there is less infiltration of B cells, CD8+ T cells, CD4+ T cells, and dendritic cells, indicating a weak immune response and a poor prognosis." (PMID 39744696, 2025). "We further investigated the expression of IRF8, CD4, RASSF2, and EVI2B in myeloid subtypes of lung adenocarcinoma." (PMID 39049031, 2024). "An automated eight-color mIF panel was evaluated to study the TME using seven antibodies, including cytokeratin 19, CD3e, CD8a, CD4, PD-1, PD-L1, F4-80 and DAPI, then was applied in six mice lung adenocarcinoma samples." (PMID 38877529, 2024).
lung adenocarcinoma (continued). "RAB11FIP1 is positively related to dendritic cells and CD4 T cells, and the low expression of RAB11FIP1 revealed a poor prognosis for lung adenocarcinoma." (PMID 35449571, 2022). "The expression levels of DFNA5 showed positive correlations to the infiltration of macrophages, CD8 + T cells, CD4 + T cells in liver hepatocellular carcinoma (LIHC), colon adenocarcinoma (COAD), and lung adenocarcinoma (LUAD)." (PMID 35248047, 2022). "The expression of T lymphocyte subset biomarkers (CD3, CD4, and CD8) in the lung adenocarcinomas was significantly varied depending on the clinical stages." (PMID 35187162, 2022). "In this study, we found that all three subsets of T lymphocytes (CD3+, CD4+, and CD8+) infiltrated into the lung adenocarcinoma as well as adjacent normal lung tissues." (PMID 35187162, 2022). "Here, we evaluated the infiltration of lung adenocarcinoma CD3+ T cell, CD4+ T cell, CD8+ T cell, Foxp3+ T cell, and their matched normal tissues." (PMID 34484468, 2021). "For example, a recent study revealed that CD4+ and CD8+ T cells are correlated with core clock molecules, especially in lung adenocarcinomas and lung squamous cell carcinomas." (PMID 34124276, 2021). "In the current study, B cell, CD8+ T cell, CD4+ T cell, macrophage, neutrophil and dendritic cell (DC) were all analyzed for their correlation with CSC, as reflected by CD44, in lung adenocarcinoma." (PMID 33372595, 2020). "In our study, we found that FGL2 expression was positively corelated to the infiltration of CD4+ T cells, CD8+ T cells, macrophages, B cells and DCs in lung adenocarcinoma." (PMID 32206449, 2020). "We evaluated the correlation between immunoreactivity of α-smooth muscle actin (α-SMA), a well-known marker of CAFs, and subpopulations of tumour-infiltrating lymphocytes determined by CD3, CD4, CD8, and Foxp3, in 27 lung adenocarcinoma tissues." (PMID 31462002, 2019). "Growth of TC1 lung adenocarcinomas was impaired in PCAF−/− mice compared to WT mice, in conjunction with decreased infiltration by CD4+Foxp3+ Treg cells but increased infiltration by host CD8 T cells." (PMID 31003455, 2019). "We first investigated the impact of Notch signaling inhibition on cell viability; 103 of purified CD4+ T cells (ten samples from peripheral bloods and seven samples from BALF of lung adenocarcinoma patients)." (PMID 30473538, 2018). "In contrast, overexpression of desmosome genes was correlated with significantly higher infiltration of activated CD4 and CD8 T-cells, but lower infiltration of activated B-cells and regulatory T-cells in lung adenocarcinoma." (PMID 29348685, 2018). "The firm adhesion overexpression group had lower infiltration of activated CD4 and CD8 T-cells, but higher infiltration of activated B-cells and NK cells in both lung adenocarcinoma and SCC." (PMID 29348685, 2018). "Notch1 mRNA expression was significantly elevated in CD4+ T cells purified from peripheral bloods and tumor site BALF in lung adenocarcinoma patients." (PMID 30473538, 2018). "From among the CD4+CD25+CD127− T-cell population, LAP TGF-β1-producing cells in control groups and lung adenocarcinoma patients were quantified and compared." (PMID 26582240, 2015). "In lung adenocarcinoma patients treated with immune checkpoint inhibitors, those with Gram-positive bacterial pneumonia show higher CD4+ T cell counts and CD4+/CD8+ T ratios than those with Gram-negative infections." (PMID 40308586, 2025). "Unlike other cancers, the fraction of CD4+ T cell immune infiltration in head and neck squamous cell carcinoma, liver cancer, lung adenocarcinoma, and lung squamous cell carcinoma was significantly decreased compared with other cancers." (PMID 40004489, 2025). "The results showed that ADRB2 and KLF4 were significantly correlated with CD4+ T cells, CD8+ T cells, macrophages, NK cells, and neutrophils infiltration in lung adenocarcinoma (LUAD), notably both showing a positive correlation with the pro-tumoral macrophages." (PMID 40276761, 2025).
lung adenocarcinoma (continued). "A study has found that there were more CD3+, CD4+, CD8+, and PD-1+ T cells in the peripheral blood of lung adenocarcinoma patients with long-term survival, indicating that the infiltration degree of immune cells in the tumor immune microenvironment is closely related to long-term survival." (PMID 37070077, 2023). "Our study presents novel insights into the critical role of TAGAP in Lung Adenocarcinoma (LUAD), emphasizing its prognostic potential, relationship with immune cell infiltration, influence on CD4+ T cell activity, and predictive value for immunotherapy responsiveness." (PMID 37744350, 2023). "Another study revealed that high Treg/CD4 ratio, but not Treg/CD8 ratio, was associated with poor survival in patients with lung adenocarcinomas." (PMID 30971280, 2019). "Similarly to CD4 cells, systemic CD8 T cells specific for lung adenocarcinoma antigens were quantified in G1 and G2 patients and found to be comparable (Fig EV5C) and distributed within non‐THD and THD subsets (Fig EV5D)." (PMID 31273938, 2019). "Neither RORγt nor AhR mRNA showed remarkable changes in peripheral CD4+ T cells between NCs and lung adenocarcinoma patients (P=0.212 and 0.186, respectively)." (PMID 30473538, 2018). "However, we found that the PD-1 expression was related to both CD4+ and CD8+ TILs in the patients with advanced lung adenocarcinoma." (PMID 29029512, 2017). "A significant increase of 2.2-fold was detected in the percentage of CD4+ROR-γt+ T-cells in lung adenocarcinoma patients compared with nonsmoking subjects." (PMID 26582240, 2015). "Higher proportions of IL-17-producing CD4+ T-cells were found in smoking control subjects and in lung adenocarcinoma patients compared to nonsmoking control subjects." (PMID 26582240, 2015). "Interestingly, in lung adenocarcinoma patients, percentages of ROR-γt+ CD4+ T-cells were higher compared to the percentages of IL-17A-producing CD4+ T-cells." (PMID 26582240, 2015). "We found a prominent increase in the degree of methylation at positions −295, −186, −54, +128 and +171 (without changing at site +122) in CD4+ T cells co-cultured with the lung adenocarcinoma cell line SPC-A1." (PMID 24244422, 2013). "Previous studies showed that B cells can promote differentiation of tumor-specific CD4+ T follicular helper cells in a neoantigen-dependent manner, which in turn enhanced CD8+ T cell effector function through IL-21 production and drove anti-tumor immunity in a mouse lung adenocarcinoma model." (PMID 40519919, 2025). "For example, in lung adenocarcinoma in mice, it was demonstrated that the bacteria Diaphorobacter nitroreducens, when combined with oxaliplatin, increased the number of CD163- and CD68-positive macrophages while reducing Treg cells (CD4 FOXP3), thus slowing tumor progression." (PMID 40075568, 2025). "In our study, the correlation between CD4+ T cells at the periphery and CD8+ T cells throughout the tumor, coupled with the lack of correlation of central CD4+ T cells, highlights the complex and spatially variable nature of the tumor immune microenvironment in lung adenocarcinoma." (PMID 39338178, 2024). "Therefore, the current study was designed to assess the expression of IDO1 and biomarkers of T cell subsets (CD3, CD4, and CD8) in the lung adenocarcinomas as well as adjacent normal lung tissues, which were resected from the patients at stage I, II, and III lung adenocarcinoma." (PMID 35187162, 2022). "Furthermore, it was also found that the number of tumor-infiltrating CD3+, CD4+, and CD8+ lymphocytes was slightly increased in stage I lung adenocarcinomas compared to that in the adjacent normal lung tissues, but it was significantly reduced in stage II and III lung adenocarcinomas." (PMID 35187162, 2022).
lung adenocarcinoma (continued). "By bioinformatic analyses using public database, they revealed the correlation between increased EXO1 expression and decreased tumor infiltrating B cells and CD4+ T cells, suggesting that EXO1 may induce an immune-suppressive tumor microenvironment in lung adenocarcinoma." (PMID 36606188, 2022). "A CD4+ LAIR2+ Treg gene signature was prognostically significant in the TCGA dataset (n = 439; hazard ratio (HR) = 1.37; 95% confidence interval (CI), 1.05–1.77, p = 0.018) and validated in NCI Director’s Challenge lung adenocarcinoma dataset (n = 488; HR = 1.54; 95% CI, 1.14–2.09, p = 0.0045)." (PMID 35008369, 2021). "However, there were no remarkable differences in Notch1 mRNA expression in either peripheral or BALF CD4+ T cells between EGFR mutation and non-EGFR mutation lung adenocarcinoma patients (P=0.852 and 0.403, respectively)." (PMID 30473538, 2018). "However, both RORγt and AhR was notably increased in BALF CD4+ T cells from tumor site in comparison with those from nontumor site in lung adenocarcinoma patients (P<0.0001)." (PMID 30473538, 2018). "Interestingly, our results reveal that CD4 and CD8 T cells are correlated with core clock molecules especially in lung adenocarcinomas and lung squamous cell carcinomas, indicating that chrono-immunotherapy may serve as a candidate option for future cancer management." (PMID 31881010, 2019). "Regarding CD4+ and CD8+ diversity, some author have reported a greater CD4+ diversity in the periphery and similar results have been described in lung adenocarcinoma, but to our knowledge, this has not been evaluated in BC." (PMID 37600765, 2023). "Contrary to our expectations, α-SMA-positive CAFs in lung adenocarcinoma were by no means correlated with lymphocyte subtypes evaluated by CD3, CD4, CD8, and Foxp3 immunohistochemistry." (PMID 31462002, 2019). "Notch2 mRNA expression was comparable in peripheral CD4+ T cells between NC and lung adenocarcinoma patients (P=0.148) and in BALF CD4+ T cells between nontumor and tumor sites (P=0.288)." (PMID 30473538, 2018). "Thus, we further showed that IL-22 expression (protein and mRNA) in CD4+ T cells from tumor site was elevated than those from nontumor site, indicating that elevated IL-22 expression in BALF might be due to the increased production by CD4+ T cells, not lung adenocarcinoma cells." (PMID 30473538, 2018). "CD4+CD25+CD127− Treg cells from the control groups and lung adenocarcinoma patients did not produce IL-10 (data not shown)." (PMID 26582240, 2015). "Furthermore, 105 of CD4+ T cells, which were from BALF of both nontumor and tumor sites of 23 stage III lung adenocarcinoma patients, were cultured with anti-CD3 antibody in the presence or absence of GSI." (PMID 30473538, 2018). "Data from one patient with lung adenocarcinomas indicated an increased number of myeloid-derived suppressor cells (MDSCs; CD206+/CD33+/HLA-DR-) and double negative (CD4-/CD8-) T cells infiltrating this tumor when compared to the corresponding numbers of these cells in the blood." (PMID 28977993, 2017). "Thus, our results show that CD4+CD25+CD127− Treg cells from the smoking and nonsmoking groups and from lung adenocarcinoma patients did not mediate suppressor activity by IL-10 production; nevertheless, CTLA-4 may be involved in the suppressor function." (PMID 26582240, 2015).